IRAK1 (interleukin 1 receptor associated kinase 1)
Diseases named in the same sentence as IRAK1 in open-access papers (continued):
Sharing a sentence is not in itself a finding about the gene and the disease.
ischemic stroke (5 papers, 2021 to 2026). A stroke disorder caused by obstruction of blood flow to the brain, due to thrombotic (local blood clot formation) or embolic (due to a blood clot or other material traveling from another site) event. "For example, MSC-derived exosomal miR-146a-5p inhibited neuro-inflammation and neurological deficits by inhibition of the interleukin 1 receptor associated kinase 1 (IRAK1)/TNF receptor associated factor 6 (TRAF6) pathway in ischemic stroke." (PMID 36552117, 2022). "miR-146a-5p improved neural deficits following ischemic stroke by downregulating microglia-induced neuroinflammation via the IRAK1/TRAF6 pathway." (PMID 36361891, 2022). "Exosomal miR-146a-5p derived from human umbilical cord mesenchymal stem cells could attenuate microglia-mediated neuroinflammation via the IRAK1/TRAF6 pathway and subsequent neural deficits following ischemic stroke." (PMID 35548775, 2022).
liver cancer (5 papers, 2016 to 2024). An epithelial or non-epithelial malignant neoplasm that arises from the liver. "Overexpression of IRAK1 has been found in several human carcinomas, including breast, endometrial, lung, and liver cancers, and is significantly associated with poor survival and unfavorable clinical parameters." (PMID 36226067, 2022). "The gender difference of liver cancer is the result of sex-associated differential production of IL-6, which relies on IL-1R/IRAK-1 signaling." (PMID 27619757, 2016). "Through its role in IL-1 and TLR signaling, IRAK1 can promote the inflammatory microenvironment that promotes the development of liver cancer." (PMID 39055701, 2024). "The siRNA results showed that STK4 knockdown upregulated the expression of IRAK1 and thus the activation of NF-κB activity, consequently impairing SS-b2-induced inhibition of liver cancer development." (PMID 37893233, 2023). "Next, more efforts will be focused on the detail mechanism of IRAK1 in the cell proliferation in liver cancer." (PMID 27619757, 2016). "In this study, frequently high expressions of IRAK1 in HCC tissues and liver cancer cells were confirmed, revealing the crucial role of IRAK1 in HCC development." (PMID 27619757, 2016). "Given the pivotal roles of STK4 and IRAK1 in the production of proinflammatory cytokines and cell proliferation in liver tumor cells, targeting STK4 and IRAK1 may present a novel strategy for inhibiting the development of inflammation-related liver cancer." (PMID 37893233, 2023). "The STK4 knockdown would upregulate IRAK1 and thus the activation of NF-κB activity revealed by the increase in the levels of proinflammatory cytokines, consequently impairing SS-b2-induced inhibition of liver cancer development." (PMID 37893233, 2023). "Moreover, STK4 regulates the transcriptional activity of YAP/TAZ in the Hippo pathway, inhibits the proliferation of liver cancer cells, and degrades in macrophages by binding and phosphorylating IRAK1." (PMID 37893233, 2023). "Moreover, IRAK1/4 inhibitor treatment at the concentration of 20 μM also caused apoptosis at 24 h and 48 h in SMMU-7721 cells, suggesting the anti-apoptosis role of IRAK1 in liver cancer." (PMID 27619757, 2016). "Among the six hub genes, C3 and DNASE1L3 are relatively low expressed in HCCLM3 and 97H liver cancer cell lines, while CTNNB1, CYBC1, IRAK1, and SERPINE1 are relatively overexpressed in liver cancer cell lines." (PMID 39055701, 2024). "The cell lines showed relatively low expression compared with normal liver cells, while CTNNB1, CYBC1, IRAK1, and SERPINE1 showed relatively high expression in HCCLM3 and 97H liver cancer cell lines compared with normal liver cells." (PMID 39055701, 2024). "Considering the coherence of high expression of IRAK1 in HCC and most liver cancer cell lines, MHCC-LM3 and SMMU-7721 were interfered by lentivirus-mediated siRNA to stably suppress IRAK1 expression." (PMID 27619757, 2016). "Based on these previous findings, we aimed to investigate whether SS-b2 inhibits PLC development, particularly inflammation-related liver cancer, by targeting STK4/IRAK1 through in vivo and in vitro experiments." (PMID 37893233, 2023). "The expression differences of the six Hub genes C3, CTNNB1, CYBC1, DNASE1L3, IRAK1, and SERPINE1 between human liver cancer cell lines and normal liver cell lines are statistically significant." (PMID 39055701, 2024). "Clinical studies have found substantial macrophage infiltration in the tumor tissues of patients with liver cancer, as well as a negative correlation between low STK4 levels and high IRAK1 levels within intracellular or peripheral blood mononuclear cells." (PMID 37893233, 2023).
psoriasis (5 papers, 2017 to 2023). An autoimmune condition characterized by red, well-delineated plaques with silvery scales that are usually on the extensor surfaces and scalp. "For example, miR-146 targets key adaptor molecules TRAF6 and IRAK1 in TLR/NFκβ mediated immune response pathways and high expression of this miRNA has been reported in Psoriasis causing inflammatory disorder." (PMID 38146363, 2023). "Finally, genome-wide association studies have identified hundreds of hypermethylated genes in psoriasis, and among them are immune-associated genes, such as TLR-7 (Toll-like receptor 7) and IRAK1 (interleukin 1 receptor associated kinase 1)." (PMID 35563264, 2022). "While this observation is in contrast with some reports, e.g., of a correlation between miR-146a and TLR4, IRAK1 in patients with coronary artery disease, others have observed reduced expression of IRAK1 by upregulation of miR-146a, e.g., in psoriasis and in senescent cells." (PMID 31294031, 2019).
acute lymphoblastic leukemia (4 papers, 2016 to 2023). Leukemia with an acute onset, characterized by the presence of lymphoblasts in the bone marrow and the peripheral blood. "Similarly, to the other findings, patient-derived T-acute lymphoblastic leukemia (T-ALL) cells also show elevated levels of IRAK1 mRNA." (PMID 37370720, 2023). "Elevated levels of IRAK1 and IRAK4 mRNA have been found in T acute lymphoblastic leukemia (T-ALL) cells." (PMID 27845762, 2016).
asthma (4 papers, 2014 to 2023). "IRAK-1, IRAK-2, and RIPK1 were the only molecules, whose gene expression was associated to both farming environment and asthma." (PMID 24603716, 2014). "We propose that miR-146a may act partially independently from IRAK1 in primary bronchial epithelial cells of patients with asthma, as previously demonstrated in primary human airway smooth muscle cells and human alveolar A549 epithelial cell line." (PMID 31798831, 2019). "Furthermore, we found that the expression of some molecules such as CD14, TLR5, TLR6, TLR8, TREM-1, but also IRAK-1 and IRAK-2 genes was significantly negatively associated with total serum IgE, atopic sensitization, or asthma." (PMID 24603716, 2014). "miR-146a mimics attenuate allergic airway inflammation by impacting ILC2 via IRAK1/TRAF6 pathways, while miR-146a inhibitors attenuate asthma via activating TLR2-signaling pathways in inflammatory monocytes." (PMID 32600285, 2020). "As the miR-146a level was reduced in the airway epithelial cells from patients with asthma, we next analyzed mRNA expression of miR-146a indirect (CXCL1 and IL-8) and direct (IRAK1) target genes in the same samples." (PMID 31798831, 2019). "Although we could show that the farm-environmental mediated up-regulation in IRAK-1, IRAK-2, and RIPK1 contributed partially to their reduced incidence of asthma." (PMID 24603716, 2014). "Also, we did not observe significant changes in IRAK1 levels in the samples from the patients with asthma regardless of the phenotype." (PMID 31798831, 2019).
cervical cancer (4 papers, 2014 to 2024). A primary or metastatic malignant neoplasm involving the cervix. "TCGA data in other squamous tumors, such as cervical cancer, identified one patient with homozygous deletion of IRAK1 and two with truncating mutations." (PMID 26527316, 2015). "miR-146a possesses potential to promote cervical cancer cell viability through modulation of IRAK1 and TRAF6." (PMID 35799607, 2022). "Conversely, depletion in IRAK1 made cervical cancer cells more vulnerable to radiation." (PMID 39451208, 2024). "Furthermore, miR-146a can enhance the viability of cervical cancer cells through regulating IRAK1 and TRAF6." (PMID 35799607, 2022). "A 2024 study on cervical cancer identified a negative correlation between IRAK1 expression and the efficacy of radiotherapy." (PMID 39451208, 2024). "Western blot results showed that IgG did not affect the protein levels of MyD88, IRAK1, and TRAF6 (data not shown), indicating that TLR4 was at least the major target involved in IgG-mediated positive regulation of LPS-induced proinflammatory cytokine production in cervical cancer cells." (PMID 25179302, 2014).
colon cancer (4 papers, 2020 to 2022). "Human colon cancer cell line HT-29 cells was selected and stimulated by IL-33 to up regulate IRAK1 protein expression." (PMID 33906562, 2021). "We analyzed expression levels of IRAK1 (RNA-Sequence data in 275 colon cancer tissues compared to 349 normal colon tissues) using TCGA-COAD database through the GEPIA2 platform." (PMID 34576039, 2021).
glioblastoma (4 papers, 2012 to 2025). The most malignant astrocytic tumor (WHO grade IV). "Anand Iyer, et.al 2012 reported that miR-146a mimics can significantly reduce the mRNA expression levels of TRAF6, IRAK1 and IRAK2 protein levels in IL-1β stimulated human astrocytes and glioblastoma cell line." (PMID 25083878, 2014). "In both the glioblastoma cell line and human astrocytes transfection with miR-146a mimic, significantly reduced IRAK-1, IRAK-2 and TRAF-6 mRNA and IRAK-1 protein after stimulation with IL-1β." (PMID 23028621, 2012).
gouty arthritis (4 papers, 2018 to 2022). "Previous studies have demonstrated that miR-146a-deficient mice develop severe gouty arthritis via TRAF6, IRAK1 and NALP3 (NACHT, LRR and PYD domain-containing protein 3)-induced inflammasome dysregulation." (PMID 32863945, 2020). "Based on our findings in mice, we hypothesized that synovial fluid from patients with RA or gout can activate synovial fibroblasts in an IL-1R/IRAK1–dependent manner." (PMID 35801586, 2022). "Synovial fluids from patients with RA and gout elicit CXCL1 and CXCL5 from synovial fibroblasts via IRAK1." (PMID 35801586, 2022). "Synthesized the results of IL-1β and TNF-α changing tendency, it is indicated that knock out miR-146a discharged the repression of TRAK6 and IRAK1 function to accelerate the production pro-inflammatory cytokines and to exacerbate the MSU-induced gouty arthritis." (PMID 29544526, 2018). "Collectively, these observations suggest that miR-146a provides negative feedback regulation of gouty arthritis development and lack of miR-146a enhances gouty arthritis via upregulation of TRAK6, IRAK-1, and the NALP3 inflammasome function." (PMID 29544526, 2018). "Our previous study used miR-146a knockout mice to test miR-146a function in a MSU-induced gouty arthritis model, and the results indicated that the lack of miR-146a enhances the inflammation level of gouty arthritis via upregulation of TRAK6, IRAK-1, and the NALP3 inflammasome function." (PMID 33935726, 2021).
Hepatitis (4 papers, 2017 to 2021). Inflammation of the liver. "Interestingly, TQ restored the reduced level of IRAK1 triggered by gastritis and hepatitis in stomach and liver and blocked the LPS-regulated degradation of IRAK1 at 2 min." (PMID 28216638, 2017). "Finally, Dt-EE displayed hepatoprotective activity in a mouse model of hepatitis induced with LPS/D-galactosamine (D-GalN) through decreasing the serum levels of alanine aminotransferase and suppressing the activation of JNK and IRAK1." (PMID 33926126, 2021).
Insulin resistance (4 papers, 2018 to 2025). Increased resistance towards insulin, that is, diminished effectiveness of insulin in reducing blood glucose levels. "Suppression of IRAK1 increases glucose uptake into skeletal muscle and decreases insulin resistance." (PMID 30279971, 2018). "The TLRs, IRAK1, and TRAF6 have been shown to be involved in innate immunity and the induction of metabolic syndromes such as insulin resistance and T2D." (PMID 37623520, 2023). "Collectively, evidence of IRAK1 involvement in insulin resistance, T2D, and NAFLD suggest that further studies of IRAK1 inhibitors in metabolic diseases are warranted." (PMID 30279971, 2018).
lymphoma (4 papers, 2015 to 2024). A malignant (clonal) proliferation of B- lymphocytes or T- lymphocytes which involves the lymph nodes, bone marrow and/or extranodal sites. "Differentially regulated genes were enriched for classical lymphoma driver genes downstream of the BCR, including MALT1 and CARD11, as well as NFATC2, TNFRSF13C (BAFF), and components of the NF-κB (RELB, IRAK1, BCL3, and TNFRSF1B) pathway." (PMID 39082968, 2024).
myocardial infarction (4 papers, 2019 to 2024). Gross necrosis of the myocardium, as a result of interruption of the blood supply to the area, as in coronary thrombosis. "Dexmedetomidine decreased myocardial infarction size and cell apoptosis through miR-146a-3p targeting IRAK1 and TRAF6 via inhibition of the NF-κB pathway." (PMID 38951872, 2024). "MiR-146a plays an important role in myocardial infarction pathology by targeting two toll-like receptors (Irak1 and Traf6)." (PMID 31092195, 2019).
non-small cell lung carcinoma (4 papers, 2019 to 2024). A group of at least three distinct histological types of lung cancer, including non-small cell squamous cell carcinoma, adenocarcinoma, and large cell carcinoma. "MiR-146a-5p demonstrated its protective effects against tumorigenesis and development of diverse neoplasms, including non-small cell lung cancer (NSCLC) by down-regulating the IRAK1 (IL-1 receptor-associated kinase 1) and TRAF6 (TNF receptor-associated factor 6) expression." (PMID 31832232, 2019). "Non-small cell lung cancer cells (NSCLC) secrete exosomal miR-146a, which inhibits TRAF-6 and IRAK-1 expression in TAMs." (PMID 38523627, 2024).
prostate carcinoma (4 papers, 2008 to 2025). A carcinoma that arises from epithelial cells of the prostate gland. "IRAK1 has been proposed that one SNP within it, when combined with high-risk genotype at TLR6-1-10, conferred a significant increase in the risk for prostate cancer, suggesting synergistic effects between sequence variants in IRAK1 and the TLR 6-1-10 gene cluster." (PMID 21655371, 2008). "Additionally, miR-146a promotes NF-kB signaling in oral, cervical, breast, and prostate cancers through the targeting of IRAK1 and TRAF6, and it enhances cell growth and proliferative signaling in several cancers—including breast, liver, lung, prostate, and gastric—by targeting EGFR." (PMID 40277937, 2025).
T-cell acute lymphoblastic leukemia (4 papers, 2015 to 2022). Acute lymphoblastic leukemia of T-cell origin. "Activation of inflammatory response pathways via IRAK1 and IRAK4 are also reported in MDS, AML, T cell acute lymphoblastic leukemia, and lymphoma." (PMID 35022428, 2022).
autoimmune hypophysitis (3 papers, 2022 to 2025). "More recently, the interleukin-1 receptor-associated kinase 1 (IRAK1) was found to be upregulated in the pituitaries of mice that developed experimental autoimmune hypophysitis." (PMID 41002414, 2025). "IRAK1 levels were elevated in the pituitary glands of mice that developed experimental autoimmune hypophysitis (EAH)." (PMID 38792088, 2024).
Cognitive impairment (3 papers, 2019 to 2025). Abnormal cognition is characterized by deficits in thinking, reasoning, or remembering. "Our data show that BCAS and eNOS deficit significantly increases IRAK1 expression and Aβ deposition, with maximum IRAK1 and Aβ observed in eNOS-/-BCAS group which may contribute to eNOS-/-BCAS induced worse cognitive impairment." (PMID 34094639, 2021).
dry eye (3 papers, 2021 to 2024). "IRAK1 is involved in a wide range of diseases such as dry eye, which highlights its potential as a therapeutic target under various conditions." (PMID 38792088, 2024). "Here, we show that miR-146 negatively regulates the inflammatory IRAK1/TRAF6/NF-κB signaling pathway in dry eye." (PMID 37433841, 2023). "The expression of IRAK1 and TRAF6 was upregulated in the corneas of dry eye model mice and during HCEC inflammation." (PMID 37433841, 2023). "The mRNA expression levels of IRAK1, TRAF6 and COX2 in the corneas of dry eye model mice were measured by RT-qPCR." (PMID 37433841, 2023). "The results showed that the protein expression levels of IRAK1 and TRAF6 were increased in the corneal epithelium and corneal stroma of the DE-group compared with those of the C-group, suggesting that IRAK1 and TRAF6 were involved in corneal inflammation in dry eye model mice." (PMID 37433841, 2023).
E. coli infection (3 papers, 2021 to 2022). "E. coli infection led to the processing of lncC11orf54-1 into mgU2-30, which effectively augmented the infection-caused inflammatory responses by facilitating the oligomerization and autophosphorylation of IRAK1." (PMID 34980188, 2022). "Since miR-146a was experimentally proven to be associated with meningitic E. coli infection, whether it also targeted IRAK1 and TRAF6 in astrocytes needed further investigation." (PMID 33985523, 2021). "We also measured the expression of IRAK1 and TRAF6 along with the E. coli infection and found that they were decreased in U251 cells upon infection." (PMID 33985523, 2021). "Importantly, different endogenous methylation statuses in IRAK1-DMR and expression levels of IRAK1, detected in DU145, LNCaP, and PC3 cells, respectively, were decisive determinants for the degree of IRAK1 activation upon uropathogenic E. coli infection." (PMID 36226067, 2022). "Moreover, miR-146a was determined to regulate the expression of IRAK1 and TRAF6 during E. coli infection." (PMID 33985523, 2021).
gastritis (3 papers, 2017 to 2024). Inflammation of the stomach. "Caffeic acid exerts anti-gastritis effects by inhibiting interleukin-1 receptor-associated kinase 1 (IRAK1), interleukin-1 receptor-associated kinase 4 (IRAK4), and TAK1 by interfering with the JNK/MAPK pathway." (PMID 38975345, 2024).
malaria (3 papers, 2023 to 2025). Malaria is a serious and sometimes fatal disease caused by a parasite that commonly infects a certain type of mosquito which feeds on humans. "However, it remains a puzzling question as to whether the degree of severity of malaria affects the TRL9 function, as in this study, IRAK1 was only expressed in the mono-infected group, while it was down-regulated in the multiple-infected group." (PMID 37910477, 2023).
ovarian carcinoma (3 papers, 2013 to 2024). A malignant neoplasm originating from the surface ovarian epithelium. "To begin evaluating the potential functional role of IRAK1 in the pathogenesis of ovarian cancer, we first performed a western blot analysis to determine IRAK1 expression." (PMID 38796478, 2024). "This study suggests that of the 17 shortlisted genes flagged as significant, the overexpressed genes IRAK1, CHEK1 and BUB1 may play an important role in ovarian cancer." (PMID 23383610, 2013). "Here, we report that the overexpressed genes IRAK1, CHEK1 and BUB1 may play an important role in ovarian cancer." (PMID 23383610, 2013).